GAL3ST1 (galactose-3-O-sulfotransferase 1)
Description:
Catalyzes the transfer of a sulfate group to position 3 of non-reducing beta-galactosyl residues in glycerolipids and sphingolipids, therefore participates in the biosynthesis of sulfoglycolipids. Catalyzes the synthesis of galactosylceramide sulfate (sulfatide), a major lipid component of the myelin sheath and of monogalactosylalkylacylglycerol sulfate (seminolipid), present in spermatocytes. Seems to prefer beta-glycosides at the non-reducing termini of sugar chains attached to a lipid moiety. Also acts on lactosylceramide, galactosyl 1-alkyl-2-sn-glycerol and galactosyl diacylglycerol (in vitro).
Synonyms: CST
Tractability: Antibody: its Gene Ontology location is reachable by antibodies, with high confidence; UniProt predicts a signal peptide or a membrane-spanning region.
Gene: Protein-coding gene on chromosome 22 (30,554,632 to 30,576,210, reverse strand). Ensembl gene ENSG00000128242.
Subcellular location: Golgi apparatus membrane
Subcellular location (Human Protein Atlas): Vesicles; Nucleoplasm
Pathways (Reactome):
Metabolism: Glycosphingolipid biosynthesis
Gene Ontology:
Molecular function: galactosylceramide sulfotransferase activity; sulfotransferase activity; galactose 3-O-sulfotransferase activity
Biological process: glycerolipid metabolic process; sphingolipid metabolic process; galactosylceramide biosynthetic process; galactosylceramide metabolic process; glycosphingolipid biosynthetic process; myelination; protein N-linked glycosylation; glycolipid biosynthetic process
Cellular component: Golgi membrane; membrane; plasma membrane
Genetic constraint (gnomAD): Loss-of-function variants: 14 observed, 28.31 expected, observed/expected ratio (o/e) 0.49, 90% interval 0.33 to 0.77. The upper end of that interval is the gene's LOEUF score, 0.77, which puts it in group 3 of 6, group 1 being the genes least tolerant of losing a copy. Missense variants: 474 observed, 614.14 expected, observed/expected ratio (o/e) 0.77, 90% interval 0.71 to 0.83. Synonymous variants: 274 observed, 275.5 expected, observed/expected ratio (o/e) 0.99, 90% interval 0.9 to 1.1.
Homologues: Orthologues: chimpanzee GAL3ST1 (99% identical), macaque GAL3ST1 (97% identical), pig GAL3ST1 (90% identical), guinea pig GAL3ST1 (89% identical), mouse Gal3st1 (84% identical), rat Gal3st1 (84% identical), zebrafish gal3st1a (58% identical), tropical clawed frog gal3st1 (57% identical), zebrafish gal3st1b (49% identical). Paralogues in human: GAL3ST4 (35% identical), GAL3ST3 (33% identical), GAL3ST2 (33% identical).
Diseases named in the same sentence as GAL3ST1 in open-access papers:
GAL3ST1 is named in the same sentence as 28 diseases in open-access papers, as found by Europe PMC text mining. Sharing a sentence is not in itself a finding about the gene and the disease. The quoted sentences say what the papers report.
breast carcinoma (4 papers, 2018 to 2025). "Expression of GAL3ST1 in breast cancer cell lines and breast cancer tissue specimens was analysed using real-time PCR, western blotting and immunohistochemistry analysis." (PMID 30400820, 2018). "We observed a correlation between GAL3ST1 immunoreactivity in cancer cells in these chemotherapy-treated breast cancer patients." (PMID 30400820, 2018). "First, we examined the expression of GAL3ST1 and sulfatides in breast cancer MCF7, T47D, SKBR3, BT-474 and MDA-MB-231 cell lines." (PMID 30400820, 2018). "Therefore, we quantified the amounts of GalCer in both cell types, and observed that overexpression of GAL3ST1 substantially decreased GalCer levels in breast cancer cells by increased synthesis of sulfatides, which strongly reinforces the importance of GalCer as an anti-apoptotic molecule." (PMID 30400820, 2018).
ovarian carcinoma (4 papers, 2010 to 2024). A malignant neoplasm originating from the surface ovarian epithelium. "Previously, overexpression of GAL3ST1 was demonstrated in the context of renal clear cell carcinoma and ovarian cancer." (PMID 36630049, 2023). "The GAL3ST-2 has been shown to be involved in CRC and gastric cancer while GAL3ST-1 has only been suggested to be involved in ovarian cancer." (PMID 26872740, 2016). "This suggests that GalCer might accumulate when there is insufficient Gal3ST1 to convert it into ST and possibly account for the finding in another type of ovarian cancer, mucinous cystadenocarcinoma, that both GalCer, and to a lesser extent ST, are elevated." (PMID 20624317, 2010). "In several human malignancies, such as renal cell carcinoma, colon and lung adenocarcinomas, and ovarian cancer, where they have been demonstrated to facilitate metastasis, STs may accumulate up as a result of increased galactosylceramide sulfotransferase (Gal3ST1) increased activity." (PMID 38943216, 2024).
clear cell renal carcinoma (2 papers, 2023 to 2024). A malignant epithelial neoplasm of the kidney characterized by the presence of lipid-containing clear cells within a vascular network. "Increased expression of GAL3ST1 was associated with decreased survival in primary clear cell renal carcinoma." (PMID 36630049, 2023). "Previously, GAL3ST1 was identified as a HIF1α target gene in renal clear cell carcinoma." (PMID 39000386, 2024).
Insulin resistance (2 papers, 2009 to 2024). Increased resistance towards insulin, that is, diminished effectiveness of insulin in reducing blood glucose levels. "Roeske-Nielsen and colleagues have identified a variation in the cerebroside sulfotransferase gene GAL3ST1 that is linked to exercise-modified insulin resistance and to Type 2 diabetes." (PMID 39290144, 2024).
kidney cancer (2 papers, 2021 to 2024). Primary or metastatic malignant neoplasm involving the kidney. "GAL3ST1 showed the highest expression levels in kidney cancer (label: KIRC) and CCA (label: CHOL); so, GAL3ST1 may be involved in the pathophysiology of CCA." (PMID 39000386, 2024). "Furthermore, employing cell culture of different human kidney- and kidney cancer-lines, the authors suggest a potential role of Gal3ST1 in promotion of cancer immune escape via Gal3ST1-sulfatide-mediated cancer cell-platelet interaction and thereby worse prognosis." (PMID 34035403, 2021).
renal carcinoma (2 papers, 2021 to 2022). A carcinoma arising from the epithelium of the renal parenchyma or the renal pelvis. "Notably, platelets bind more efficiently to renal cancer cells with high GAL3ST1-sulfatide expression than to GAL3ST1-sulfatide-negative renal cancer cells, which protects ccRCC cells from NK cell-mediated cytotoxicity." (PMID 35659268, 2022).
biliary tract cancer (1 paper, 2024). "The loss of GAL3ST1 showed a negative effect on growth in 30 out of 34 biliary tract cancer cell lines from the DepMap database." (PMID 39000386, 2024).
cholangiocarcinoma (1 paper, 2024). A carcinoma that arises from the intrahepatic biliary tree (intrahepatic cholangiocarcinoma) or from the junction, or adjacent to the junction, of the right and left hepatic ducts (hilar cholangiocarcinoma). "Inhibiting sulfatide synthesis by targeting GAL3ST1 holds potential as a new therapeutic strategy in cholangiocarcinoma." (PMID 39000386, 2024).
demyelinating disorders (1 paper, 2025). "Studies have shown that alterations in sulfatide metabolism, including changes in GAL3ST1 expression, are linked to neurodegenerative diseases and demyelinating disorders." (PMID 41146907, 2025).
hyperplastic polyp (1 paper, 2016). A polyp found mainly in the stomach and colon. "Finally, if also the patient (Co-657) with five hyperplastic polyps at an age of 73 years was considered a gene carrier, yet another three genes (SF3A1, GAL3ST1, TRIOBP) could be excluded." (PMID 26872740, 2016).
invasive ductal carcinoma (1 paper, 2018). "Accordingly, a clinical study on GAL3ST1 expression in invasive ductal carcinoma revealed that its elevated level is associated with better prognosis." (PMID 30400820, 2018). "The expression of GAL3ST1 in paraffin sections of invasive ductal carcinoma (IDC) specimens was studied using IHC." (PMID 30400820, 2018).
melanoma (1 paper, 2024). A malignant, usually aggressive tumor composed of atypical, neoplastic melanocytes. "Second, we observed a significant upregulation of GAL3ST1 and FERT expression associated with the ectopic BORIS expression in BORIS-negative cell lines, HEK293T (human embryonic kidney) and MDA-MB-435 (melanoma cell line), respectively." (PMID 38297316, 2024).
tumor (8 papers, 2017 to 2025). "UGT8 and GAL3ST1 showed higher mRNA levels in iCCA tumor tissue as well as in CCA cell lines from different anatomical regions of the biliary tract compared to normal tissue/cells." (PMID 39000386, 2024). "Further studies are needed to determine the role of GAL3ST1 in CCA tumor biology by evaluating additional cell lines and in vivo studies in experimental models of CCA." (PMID 39000386, 2024). "UGT8 and GAL3ST1 showed higher expression levels in tumor tissue compared to normal tissue, with significance reached for GAL3ST1." (PMID 39000386, 2024). "On the other hand, enhanced synthesis of sulfatides through overexpression of GAL3ST1 results in increased metastatic potential of tumor cells, indicating diversion of apoptotic to pro-survival signaling." (PMID 36630049, 2023). "The HIF1-galactose-3-O-sulfotransferase 1 (GAL3ST1)-sulfatide axis enhances immune escape in ccRCC by increasing tumor cell-platelet binding." (PMID 35659268, 2022). "Accordingly, GAL3ST1 is an HIF1-responsive gene that contributes to ccRCC development by promoting tumor immune escape." (PMID 35659268, 2022). "Paraffin sections from patients with renal malignancy (ccRCC, pRCC, chRCC) were analyzed for the localization and intensity of GAL3ST1-Expression in tumor and its microenvironment, including peritumoral kidney tissue." (PMID 34035403, 2021). "Tumor-free kidney and peritumoral kidney tissue showed typically weak to moderate Gal3ST1 expression, predominantly in tubular system (proximal > distal tubuli)." (PMID 34035403, 2021). "Higher expression of GAL3ST1 was observed in less aggressive G1 tumours than in highly aggressive G3 tumours (Mann Whitney test, p < 0.01)." (PMID 30400820, 2018). "Using IHC, we showed that the expression of GAL3ST1 decreased with tumour malignancy grade with significant differences in GAL3ST1 expression in G1 vs G3 tumours, and that high expression of GAL3ST1 in IDC cells is associated with longer OS of patients." (PMID 30400820, 2018). "Positive cytoplasmic expression of GAL3ST1 was observed in tumour cells in 127 (54.74%) of the 232 examined cases." (PMID 30400820, 2018). "Furthermore, the VHL-HIF axis regulates GAL3ST1 in ccRCC, which affects the tumor's immune evasion capabilities." (PMID 39781455, 2025). "In a small cohort of patients from the Maastricht University Medical Center and Uniklinik RWTH Aachen, UGT8 and GAL3ST1 expression was measured by quantitative real-time PCR (qRT-PCR) in 6 tumor tissue and 10 tumor-distal liver specimens from patients with intrahepatic CCA." (PMID 39000386, 2024). "We demonstrated an anti-tumor effect by deleting the GAL3ST1 gene in TFK1 cells." (PMID 39000386, 2024). "Moreover, GAL3ST1 is an HIF1 target gene, and its expression is induced upon loss of von Hippel-Lindau (VHL) tumor suppressor, leading to accumulation of its enzymatic product sulfatide." (PMID 35659268, 2022). "Hence, our results indicate that potential prognostic value of (lipid) sulfatide, as an abundant and in part immunomodulating component of RCC microenvironment, cannot be translated to (enzyme / protein) Gal3ST1 levels in tumor cells." (PMID 34035403, 2021). "Specific, mainly cytoplasmic tumor cell positivity for Gal3ST1 could be detected in investigated histological cancer types, in various intensity grades." (PMID 34035403, 2021). "Moreover, the authors identify HIF-mediated increased synthesis of Gal3ST1, implying the effect of hypoxic tumor microenvironment on Gal3ST1 expression." (PMID 34035403, 2021). "In general, any degree of tumor-specific Gal3ST1 positivity was evident in 81% (n = 96) cases." (PMID 34035403, 2021). "However, this study indicates that the inhibition of GAL3ST1 may have therapeutic potential in CCA by inhibiting tumor growth and aggressiveness." (PMID 39000386, 2024). "While mRNA levels of C3, AKR1C3, GAL3ST1 were not completely correlated with tumor pathological grades and stages." (PMID 37035174, 2023).
tumor (continued). "Under hypoxic conditions, HIF1A induces activation of target genes (PD-L1, CCL28, and GAL3ST1), resulting in immune cell apoptosis, and drives expression of the negative immune checkpoint regulator VSIR and MIC genes to evade immune surveillance and ultimately promote tumor immune escape." (PMID 35659268, 2022).
cancer (5 papers, 2015 to 2024). A tumor composed of atypical neoplastic, often pleomorphic cells that invade other tissues. "The expression body map, normalized to transcripts per million (TPM) revealed the median expression of UGT8 and GAL3ST1 in different human cancers." (PMID 39000386, 2024). "To investigate whether BORIS activates cancer-testis-specific transcription in somatic cells, we analyzed Gal3st1 expression in NIH3T3 cells expressing either EV or BORIS." (PMID 38297316, 2024). "Consequently, thousands of intragenic and intergenic BORIS binding sites in K562 cells have the potential to function as alternative promoters in cancer cells, mirroring the scenario observed with GAL3ST1 and FERT genes." (PMID 38297316, 2024). "Therefore, the direct binding of BORIS to intronic regions concurrently bound by CTCF in FER and GAL3ST1 genes appears to be associated with transforming these CTCF sites into active internal promoters, thereby driving alternative cancer-testis-specific transcriptional start sites." (PMID 38297316, 2024). "We first compared epigenetic changes accompanying BORIS’s binding to the intronic sites of GAL3ST1 and FER genes in cancer cells to that in BORIS-negative cells." (PMID 38297316, 2024). "In this study, we showed that both GAL3ST1 and FER testis-specific transcripts are abnormally activated in cancer cells, coinciding with aberrant BORIS expression and its binding to the intronic promoters." (PMID 38297316, 2024). "For example, the testis-specific promoter of the GAL3ST1 gene was silenced when occupied by CTCF alone in most BORIS-negative cell lines, but it was activated in BORIS-positive cells (germ and cancer) when co-occupied by CTCF and BORIS." (PMID 26268681, 2015). "To expand the analysis initially performed on GAL3ST1 and FERT genes to a genome-wide scope, we aimed to explore the potential role of BORIS binding sites in activating alternative transcriptional start sites in both male germline and cancer cells." (PMID 38297316, 2024). "Similarly to GAL3ST1, PRAME and FOXA3 genes were also silent under CTCF occupancy, but were activated upon CTCF and BORIS co-binding in both cancer and germ cells." (PMID 26268681, 2015). "Therefore, both GAL3ST1 and FERT are male germ cell-specific products of genes expressed in somatic cells and are thus good candidates through which we can study BORIS-specific regulation either in cancers or our cell model systems." (PMID 38297316, 2024).
GAL3ST1 also shares sentences with these, for which no sentence is quoted: metachromatic leukodystrophy (3 papers); renal cell carcinoma (2); Type 2 Diabetes (2); breast tumours (1); colon cancers (1); gastric cancer (1); Hypertension (1); kidney tumor (1); lung adenocarcinoma (1); lysosomal storage disorders (1); mucinous cystadenocarcinoma (1); neurodegenerative disease (1); prion disease (1); sterility (1).